RNU6-771P (RNA, U6 small nuclear 771, pseudogene)
Synonyms: RNU6-1185P
Gene: Small nuclear RNA gene on chromosome 1 (13,279,125 to 13,279,231, reverse strand). Ensembl gene ENSG00000207511.
Homologues: Orthologues: macaque U6 (86% identical), rabbit U6 (83% identical), mouse Gm22950 (82% identical), dog U6 (81% identical), guinea pig U6 (81% identical), rabbit U6 (75% identical). Paralogues in human: RNU6-1072P (100% identical), RNU6-1323P (92% identical), RNU6-25P (88% identical), RNU6-35P (88% identical), RNU6-1 (87% identical), RNU6-1316P (87% identical), RNU6-2 (87% identical), RNU6-29P (87% identical), RNU6-338P (87% identical), RNU6-3P (87% identical), RNU6-48P (87% identical), RNU6-4P (87% identical), and 1284 more.